LDHC (lactate dehydrogenase C)
Description:
Possible role in sperm motility.
Synonyms: CT32; LDH3; LDHX
Tractability: Small molecule: a structure with a bound ligand is known. PROTAC: ubiquitination databases record sites on it.
Gene: Protein-coding gene on chromosome 11 (18,412,306 to 18,452,063, forward strand). Ensembl gene ENSG00000166796.
Subcellular location: Cytoplasm
Subcellular location (Human Protein Atlas): Cytosol; End piece; Mid piece; Principal piece
Pathways (Reactome):
Metabolism: Pyruvate metabolism
Gene Ontology:
Molecular function: L-lactate dehydrogenase (NAD+) activity; protein binding; catalytic activity; oxidoreductase activity; oxidoreductase activity, acting on the CH-OH group of donors, NAD or NADP as acceptor
Biological process: lactate biosynthetic process from pyruvate; lactate metabolic process; pyruvate catabolic process; ATP biosynthetic process; flagellated sperm motility
Cellular component: cytosol; extracellular exosome; nucleus; mitochondrion; motile cilium; oxidoreductase complex; cilium; cytoplasm
Genetic constraint (gnomAD): Loss-of-function variants: 6 observed, 5.13 expected, observed/expected ratio (o/e) 1.17, 90% interval 0.62 to 1.87. That is too few expected variants to judge how well the gene tolerates losing a copy. Missense variants: 73 observed, 70.67 expected, observed/expected ratio (o/e) 1.03, 90% interval 0.85 to 1.25. Synonymous variants: 30 observed, 25.11 expected, observed/expected ratio (o/e) 1.19, 90% interval 0.89 to 1.62.
Homologues: Orthologues: macaque LDHC (94% identical), chimpanzee LDHC (91% identical), pig LDHC (90% identical), rabbit LDHC (89% identical), dog LDHC (89% identical), guinea pig LDHC (83% identical), mouse Ldhc (74% identical), rat Ldhc (73% identical). Paralogues in human: LDHA (75% identical), LDHB (70% identical), LDHAL6B (67% identical), LDHAL6A (66% identical), MDH2 (24% identical).
Diseases named in the same sentence as LDHC in open-access papers:
LDHC is named in the same sentence as 60 diseases in open-access papers, as found by Europe PMC text mining. Sharing a sentence is not in itself a finding about the gene and the disease. The quoted sentences say what the papers report.
breast cancer (22 papers, 2012 to 2026). A primary or metastatic malignant neoplasm involving the breast. "TIMER and TIDE analyses revealed that tumor LDHC expression is associated with T cell dysfunction in breast cancer and poorer post-immunotherapy survival in melanoma." (PMID 40108668, 2025). "Following our observation that decreased LDHC expression in breast cancer cells was associated with enhanced T cell functionality, we performed an in-depth analysis of LDHC-associated changes in immune-related molecules." (PMID 40108668, 2025). "A recent study demonstrated that demethylation of the LDHC promoter was associated with poor prognosis in patients with breast cancer." (PMID 36551514, 2022). "Lactate dehydrogenase C (LDHC) is an isoform of the lactate dehydrogenase (LDH) family whose elevated expression was observed in serum-derived exosomes as well as tissue of breast cancer patients and associated with adverse clinical outcomes, poor survival, and remission." (PMID 37719007, 2023). "Moreover, we recently demonstrated that LDHC is an immunogenic tumor‐associated antigen that can elicit a cytotoxic immune response against breast cancer cells." (PMID 34050611, 2022). "Further studies are required to elucidate the molecular mechanisms by which LDHC modulates immune responses in breast cancer." (PMID 40108668, 2025). "Multiplex cytokine assays and flow cytometry were used to assess the effect of LDHC knockdown on the secretion of inflammatory molecules and expression of immune checkpoint molecules in breast cancer cells and cancer cell-immune cell co-cultures." (PMID 40108668, 2025). "For these analyses, we utilized the basal-like MDA-MB-468 breast cancer cell line, which demonstrated robust LDHC knockdown efficiency and the highest increase in T cell-mediated cancer cell cytotoxicity following LDHC silencing." (PMID 40108668, 2025). "Silencing LDHC in breast cancer cell lines (MDA-MB-468, BT-549, HCC-1954) enhanced early T cell activation and cytolytic activity." (PMID 40108668, 2025). "In breast cancer cell lines, silencing LDHC leads to nuclear abnormalities, DNA damage, and increased apoptosis." (PMID 40860340, 2025). "To date, LDHC has been found to be highly expressed in tumors such as lung cancer, melanoma, breast cancer, hepatocellular carcinoma, and prostate cancer." (PMID 40270965, 2025). "In accordance, silencing of LDHC in three distinct breast cancer cell lines enhanced T cell activation and cytolytic activity." (PMID 40108668, 2025). "We investigated the relationship between aberrant LDHC tumor expression, immune cell infiltration, and T cell function in breast cancer using various deconvolution methods." (PMID 40108668, 2025). "have identified the immunogenic LDHC-derived peptides P11 (LDHC41–55) and P73 (LDHC288–303) that elicited CD8+ T-cell responses against HLA-A*0201/LDHC-positive breast cancer cells, demonstrating increased IFN-γ secretion and cytolytic activity." (PMID 40270965, 2025). "We previously demonstrated that LDHC is an immunogenic antigen and plays a role in maintaining genomic stability and mitotic fidelity in breast cancer cell lines, safekeeping tumor cellular fitness." (PMID 38596293, 2024). "More specifically, we found that LDHC silencing greatly reduces tumor cellular fitness and the long-term survival of basal-like breast cancer cells." (PMID 39001513, 2024). "The comparative analysis of three breast cancer cell lines revealed cell line-dependent differences in the cellular phenotype and molecular landscape following LDHC silencing." (PMID 39001513, 2024). "We recently provided experimental evidence to support this approach, whereby silencing of LDHC greatly sensitized breast cancer cells to treatment with cisplatin and olaparib." (PMID 38596293, 2024). "Here, we explored the molecular mechanisms associated with LDHC silencing in two basal-like breast cancer cell lines, MDA-MB-468 and BT-549, and a Her2-enriched breast cancer cell line, HCC-1954." (PMID 39001513, 2024).
breast cancer (continued). "We previously demonstrated that the stable silencing of LDHC dysregulates the DNA damage response and affects the mitotic fidelity and long-term survival of breast cancer cells, particularly in basal-like breast cancer cell lines." (PMID 39001513, 2024). "We previously demonstrated the aberrant expression of LDHC in breast tumor tissues of the TCGA breast cancer dataset, in particular in basal-like and Her2-enriched breast tumors, which was associated with worse overall and disease-specific survival." (PMID 39001513, 2024). "LDHC targeting demonstrates a beneficial response, particularly in basal-like breast cancer cellular models, through the inhibition of the LDHC-STAT3 axis." (PMID 39001513, 2024). "LDHC acetylation level is known to control different types of cancers like breast cancer, and testicular and colon cancer." (PMID 37446160, 2023). "Studies have confirmed that LDHC mRNA is expressed in various tumor tissues such as lung cancer, melanoma, breast cancer, and kidney cancer." (PMID 37006626, 2023). "Since we demonstrated that LDHC silencing increases DNA damage accumulation in breast cancer cells with alterations in the expression of DNA damage sensors upstream of the DDR pathway, we explored the sensitivity of shLDHC cells to olaparib and cisplatin." (PMID 34050611, 2022). "Analysis of the TCGA breast cancer dataset revealed a trend of increased LDHC expression in breast tumor tissue compared to normal tissue." (PMID 34050611, 2022). "LDHC silencing‐induced apoptosis in all four breast cancer cell lines, as demonstrated by an increase in caspase 3 cleavage." (PMID 34050611, 2022). "Here, we show that targeting LDHC in breast cancer cells dysregulates the cell cycle with increased DNA damage, compromising long‐term cell survival." (PMID 34050611, 2022). "Of note, these observations were consistent in three basal‐like breast cancer cell lines and in one luminal A cell line, indicating the broad applicability of LDHC function in maintaining mitotic fidelity." (PMID 34050611, 2022). "Silencing LDHC in four breast cancer cell lines significantly increased the presence of giant cells, nuclear aberrations, DNA damage, and apoptosis." (PMID 34050611, 2022). "In four breast cancer cell lines, silencing LDHC significantly increased the number of giant cells, nuclear abnormalities, DNA damage, and apoptosis." (PMID 35885460, 2022). "Strikingly, silencing of LDHC significantly decreased the colony formation ability, hence long‐term survival, of all four breast cancer cell lines." (PMID 34050611, 2022). "Our previous publications have reported that serum exosomal LDHC overexpression can serve as a multipurpose biomarker for early diagnosis, efficacy assessment, and recurrence monitoring in breast cancer (BC) patients." (PMID 34778372, 2021). "Next, we primed T cells with autologous peptide-pulsed dendritic cells for 2 weeks after which the LDHC-specific T cells were incubated with the various breast cancer cell lines for 4 h." (PMID 31932876, 2020). "More specifically, we observed reduced IFN-γ secretion and a complete lack of cytolytic activity of T cells in co-culture with low LDHC expressing cancer cells, which was confirmed, in a second breast cancer cell line model." (PMID 31932876, 2020). "LDHC41−55 and LDHC288−303-primed T cells exhibited increased IFN-γ secretion and cytolytic activity against HLA-A*0201 breast cancer cell lines with endogenous LDHC expression." (PMID 31932876, 2020). "More specifically, we found an increase in IFN-γ secretion by CD8 + T cells and cancer-cell-killing of HLA-A*0201/LDHC positive breast cancer cells by LDHC41−55- and LDHC288−303-induced T cells, albeit with a possible antigen recognition threshold." (PMID 31932876, 2020). "The results preliminarily show that serum and exosomal LDHC mRNA can be utilized as an effective biomarker of breast cancer." (PMID 33035196, 2020).
breast cancer (continued). "The PP2- and PP8-specific T cells displayed cytolytic activity against breast cancer cells with endogenous LDHC expression within a HLA-A*0201 context." (PMID 31932876, 2020). "We have previously reported that the positive rates of LDH-C4, serum LDHC and exosomal LDHC are 91.55% (130 / 145), 91.66% (22 / 24) and 87.50% (21 / 24) in breast cancer tissues using a microarray analysis, which are consistent with the results of this study." (PMID 33035196, 2020). "Preliminary work in our group shows that LDHC is strongly expressed in breast cancer, thereby supporting its potential as a biomarker and/or immunotherapeutic target for breast cancer, including the aggressive triple negative breast cancer subtype." (PMID 30400835, 2018). "Moreover, we recently demonstrated that silencing of LDHC in breast cancer cells leads to DNA damage accumulation and dysregulation of the cell cycle, impairing clonogenic ability." (PMID 40108668, 2025). "To investigate the role of LDHC tumor expression in regulating T cell function, we generated breast cancer cell models with varying levels of LDHC expression by knocking down LDHC in two basal-like cell lines (MDA-MB-468, BT-549) and one Her2-enriched cell line." (PMID 40108668, 2025). "To further investigate this, we examined whether LDHC expression in basal-like and Her2-enriched breast cancer cells impacts immune cell function." (PMID 40108668, 2025). "Utilizing co-culture models, we found that LDHC expression in breast cancer cells likely promotes an immunosuppressive tumor microenvironment, impairing immune cell function through alterations in cytokine secretion and modulation of immune checkpoint expression." (PMID 40108668, 2025). "Furthermore, Naik and Decock reported that knockdown of LDHC expression increased DNA damage and apoptosis in breast cancer cells." (PMID 40270965, 2025). "We found that the stable silencing of LDHC drastically compromised breast cancer cell survival through the accumulation of DNA damage, microtubule destabilization and cell cycle dysregulation, resulting in enhanced cell death, mitotic catastrophe, and senescence." (PMID 39001513, 2024). "Using three breast cancer cell lines, we found that the effect of LDHC targeting on tumor cell survival was negatively impacted by the activation of the STAT3 pathway in some cell lines and could be restored by STAT3 inhibition." (PMID 39001513, 2024). "Using multiple breast cancer cell line models, we show that LDHC is involved in maintaining mitotic fidelity and genomic integrity and that targeting of LDHC improves treatment response to DNA damage response targeted therapy using DNA damage inducers and DNA repair inhibiting agents." (PMID 34050611, 2022). "Here, we report that targeting of LDHC in breast cancer cells has the potential to tip the fine balance between tolerable and excessive levels of genomic damage in favor of the latter and as such to sensitize cancer cells to DNA damage inducers and DNA damage repair inhibitors." (PMID 34050611, 2022). "Analysis of breast cancer patient cohorts from The Cancer Genome Atlas (TCGA) and Molecular Taxonomy of Breast Cancer International Consortium (METABRIC) indicates that upregulation of LDHC expression is associated with a poor prognosis." (PMID 35885460, 2022). "Although it was originally assumed that LDHC was strictly present in the testes, several studies have been published that LDHC is present in a range of cancer tissues, including lung cancer (47%), melanoma (44%), breast cancer (35%), and some prostate cancers." (PMID 36551514, 2022). "This phenotype of mitotic dysregulation upon LDHC silencing was observed in all four breast cancer cell lines, and however, the molecular mechanistic underpinnings of these observations may vary between cell lines based on their genetic landscape." (PMID 34050611, 2022).
breast cancer (continued). "Indeed, we found that silencing LDHC sensitizes breast cancer cells to olaparib and cisplatin albeit at different extents, thereby improving the efficacy of either treatment with subtle differences in cell line sensitivity." (PMID 34050611, 2022). "Moreover, we were able to demonstrate the functional activity of the peptide-specific CD8 + T cells against breast cancer cell lines with endogenous LDHC expression, albeit with a constraint of an antigen threshold." (PMID 31932876, 2020). "Moreover, our results suggest that there is a plausible threshold of LDHC expression to elicit an anti-tumor immunity since we observed attenuated T cell responses against the HLA-A*0201 breast cancer cell line following LDHC silencing." (PMID 31932876, 2020). "Thus, we used flow cytometry to determine the expression of LDHC across a panel of breast cancer cell lines, including HLA-A2− and HLA-A2+ cell lines." (PMID 31932876, 2020). "In our previous work, IHC staining has been carried out to determine LDH-C4 expressions in 145 breast cancer tissue microarrays, and expression levels of peripheral serum and exosomal LDHC mRNAs in 75 breast cancer patients have been quantitated using RT-PCR analysis." (PMID 33035196, 2020). "We used shRNA to reduce the expression of LDHC in the HLA-A*0201 positive HCC1500 breast cancer cell line, resulting in A2 + /LDHC low cells with silenced LDHC expression (A2 + /low), in addition to the parental A2 + /LDHC high cells with endogenous high expression of LDHC (A2 + /high)." (PMID 31932876, 2020). "Currently, few studies report biofunctions of LDH-C4 in tumor cells, and some find that LDHC mRNA is expressed in various tumors with positive rates of expressions of its spliceosomes up to 47% in lung cancer, 44% in melanoma, 35% in breast cancer and 15% in colon cancer." (PMID 33035196, 2020). "Thus, LDHC is a viable target for breast cancer treatment in a subtype-specific manner." (PMID 39001513, 2024). "Furthermore, whether LDHC-targeted therapy, either as monotherapy or combination therapy, could be beneficial to patients with other breast cancer subtypes remains to be determined." (PMID 39001513, 2024). "Next, we sought to validate our findings in one additional basal-like breast cancer cell line, BT-549, and investigated whether LDHC silencing differentially affects gene expression in other breast cancer subtypes through a comparative analysis of the Her2-enriched HCC-1954 cell line." (PMID 39001513, 2024). "To conclude, we believe that developing LDHC‐specific therapeutic interventions using specific chemical inhibitors or siRNA delivery approaches presents an attractive paradigm to enhance the efficacy of current drugs and to improve clinical outcome in breast cancer." (PMID 34050611, 2022). "Silencing LDHC significantly downregulated the mRNA expression of PD-L1, CD80 and GAL-9 in MDA-MB-468 breast cancer cells." (PMID 40108668, 2025). "We observed a positive correlation between LDHC expression and B cell infiltration in Her2-enriched tumors, macrophages and dendritic cells in luminal B tumors, and CD4 + T cells across all breast cancer samples." (PMID 40108668, 2025). "Thus, LDHC-targeted therapy could be a viable therapeutic approach for a subset of breast cancer patients, particularly patients with basal-like breast cancer, whereas patients carrying Her2-enriched tumors may likely benefit more from monotherapy with STAT3 inhibitors." (PMID 39001513, 2024). "Numerous studies have attempted to explain the roles of LDHC/LDH-C4 in the occurrence and development of multiple human cancers, such as renal cell carcinoma, hepatocellular carcinoma (HCC), and breast cancer (BC)." (PMID 35814471, 2022). "Our previous study series reported similar performances of LDHC/LDH-C4, a cancer-testis antigen, in diagnosis and relapse prediction and efficacy evaluation for breast cancer and hepatocellular carcinoma patients." (PMID 34778372, 2021).